ILK (integrin linked kinase)
Description:
Scaffold protein which mediates protein-protein interactions during a range of cellular events including focal adhesion assembly, cell adhesion and cell migration. Regulates integrin-mediated signal transduction by contributing to inside-out integrin activation (By similarity). Recruits PARVA and LIMS1/PITCH to form the heterotrimeric IPP (ILK-PINCH-PARVIN) complex which binds to F-actin via the C-terminal tail of LIMS1 and the N-terminal region of PARVA, promoting F-actin filament bundling, a process required to generate force for actin cytoskeleton reorganization and subsequent dynamic cell adhesion events such as cell spreading and migration. Binding to PARVA promotes effective assembly of ILK into focal adhesions while PARVA-bound ILK can simultaneously engage integrin-beta cytoplasmic tails to mediate cell adhesion. Plays a role with PARVG in promoting the cell adhesion and spreading of leukocytes. Acts as an upstream effector of both AKT1/PKB and GSK3. Mediates trafficking of caveolae to the cell surface in an ITGB1-dependent manner by promoting the recruitment of IQGAP1 to the cell cortex which cooperates with its effector DIAPH1 to locally stabilize microtubules and allow stable insertion of caveolae into the plasma membrane (By similarity). Required for the maintenance of mitotic spindle integrity by promoting phosphorylation of TACC3 by AURKA. Associates with chromatin and may act as a negative regulator of transcription when located in the nucleus.
Synonyms: HEL-S-28; ILK-1; ILK-2; P59; p59ILK
Tractability: Small molecule: a structure with a bound ligand is known; a high-quality ligand is known; it has a high-quality binding pocket; it belongs to a druggable protein family. Antibody: UniProt places it where antibodies can reach, with high confidence; its Gene Ontology location is reachable by antibodies, with medium confidence. PROTAC: ubiquitination databases record sites on it; its protein half-life has been measured; a small molecule that binds it is known.
Target class: TKL protein kinase group; TKL protein kinase ILK subfamily; Protein Kinase; TKL protein kinase MLK family; Enzyme; Kinase
Gene: Protein-coding gene on chromosome 11 (6,603,708 to 6,610,874, forward strand). Ensembl gene ENSG00000166333.
Subcellular location: Cell junction, focal adhesion; Cell membrane; Cell projection, lamellipodium; Cytoplasm, myofibril, sarcomere; Cytoplasm; Nucleus; Cytoplasm, cytoskeleton, microtubule organizing center, centrosome; Cytoplasm, cell cortex
Subcellular location (Human Protein Atlas): Focal adhesion sites; Actin filaments; Cytosol; Nucleoplasm
Pathways (Reactome):
Cell-Cell communication: Cell-extracellular matrix interactions; Localization of the PINCH-ILK-PARVIN complex to focal adhesions
Gene Ontology:
Molecular function: ATP binding; integrin binding; magnesium ion binding; protein binding; protein kinase binding; protein serine/threonine kinase activity; protein-macromolecule adaptor activity; signaling receptor binding; protein kinase activity
Biological process: actin filament bundle assembly; actin filament network formation; cell morphogenesis; integrin-mediated signaling pathway; mitotic spindle organization; platelet aggregation; positive regulation of canonical NF-kappaB signal transduction; positive regulation of canonical Wnt signaling pathway; positive regulation of DNA-templated transcription; positive regulation of signal transduction; positive regulation of substrate adhesion-dependent cell spreading; substrate adhesion-dependent cell spreading; tumor necrosis factor-mediated signaling pathway; cell differentiation; cell-matrix adhesion; anatomical structure morphogenesis; caveola assembly; outflow tract morphogenesis; positive regulation of BMP signaling pathway; positive regulation of osteoblast differentiation; protein localization to cell cortex
Cellular component: centrosome; chromatin; cytoplasm; cytosol; focal adhesion; membrane; nucleus; plasma membrane; cell cortex; lamellipodium; sarcomere
Genetic constraint (gnomAD): Loss-of-function variants: 37 observed, 61.02 expected, observed/expected ratio (o/e) 0.61, 90% interval 0.47 to 0.8. The upper end of that interval is the gene's LOEUF score, 0.8, which puts it in group 3 of 6, group 1 being the genes least tolerant of losing a copy. Missense variants: 528 observed, 624.32 expected, observed/expected ratio (o/e) 0.85, 90% interval 0.79 to 0.91. Synonymous variants: 231 observed, 213.45 expected, observed/expected ratio (o/e) 1.08, 90% interval 0.97 to 1.21.
Gene-disease validity (ClinGen):
ClinGen rates the evidence that ILK causes each of these diseases.
dilated cardiomyopathy (autosomal dominant): Limited. Cardiomyopathy which is characterized by dilation and contractile dysfunction of the left and right ventricles.
Homologues: Orthologues: macaque ILK (100% identical), dog ILK (99% identical), guinea pig ILK (99% identical), mouse Ilk (99% identical), rat Ilk (99% identical), chimpanzee ILK (99% identical), rabbit ILK (98% identical), pig ILK (96% identical), zebrafish ilk (87% identical), tropical clawed frog ilk (80% identical), Drosophila melanogaster Ilk (60% identical), Caenorhabditis elegans pat-4 (58% identical). Paralogues in human: TNNI3K (23% identical), MAP3K9 (23% identical), MAP3K10 (23% identical), MAP3K21 (22% identical), MAP3K11 (21% identical), LIMK1 (20% identical), LIMK2 (19% identical), MAP3K13 (19% identical), LRRK2 (19% identical), KSR1 (19% identical), KSR2 (19% identical), MAP3K12 (19% identical), and 11 more.
Diseases named in the same sentence as ILK in open-access papers:
ILK is named in the same sentence as 230 diseases in open-access papers, as found by Europe PMC text mining. Sharing a sentence is not in itself a finding about the gene and the disease. The quoted sentences say what the papers report.
breast cancer (98 papers, 2003 to 2026). A primary or metastatic malignant neoplasm involving the breast. "ILK pathways are linked to multidrug resistance in breast cancer, with both in vitro and in vivo studies showing elevated ILK expression associated with disease progression." (PMID 41537745, 2026). "Integrin‐linked kinase (ILK) is a serine/threonine protein kinase that has been widely established as a critical driver of breast cancer progression, metastasis, and therapeutic resistance." (PMID 41537745, 2026). "On the contrary, it has been reported that loss of ILK abrogates the mechanosensing capability of breast cancer cells and blocks tumorigenic and metastatic potential." (PMID 35481240, 2022). "For instance, hypoxic breast cancer cells have been shown to release EVs containing integrin-linked kinase (ILK) that increase epithelial cell migration, a requirement for epithelial-to-mesenchymal transition (EMT)." (PMID 35454774, 2022). "ILK pathway: Activation of oncogenes leads to overgrowth of cancer cells, which is the hallmark of the progression of a malignant tumor, like breast cancer." (PMID 34991439, 2022). "ILK signaling has been implicated in the mechanotransduction-mediated regulation of autophagy at sites of distant metastasis in breast cancer." (PMID 35804980, 2022). "In patients with breast cancer, high levels of expression of ILK and YAP are associated with increased disease stage and lymph node metastases, linking this signaling axis clinically to metastatic progression." (PMID 35804980, 2022). "The outcomes of seven in vitro and in vivo studies on breast cancer cells indicated that suppression of the Notch pathway with DAPT suppressed the activation of Notch by integrin-linked kinase (ILK)." (PMID 33673088, 2021). "Integrin-linked kinase (ILK) is a signaling protein that was recently shown to be an EV cargo upregulated in sEVs released from hypoxic estrogen receptor positive breast cancer cells." (PMID 34205051, 2021). "EA was identified as an inhibitor of integrin-linked kinase (ILK) in the breast cancer cell line, MCF-7 as well." (PMID 33669953, 2021). "In mouse mammary carcinoma cells, an integrin-linked kinase- and mDia2-induced integrin-actin cascade regulated tumor initiation." (PMID 32728066, 2020). "Knockdown of FAK, Integrin linked kinase (ILK), talin, and zyxin in breast cancer (MCF7) cells leads to enlarged FA and decreased migration." (PMID 31781558, 2019). "Time-lapse microscopy using breast cancer cells indicated that following mitotic arrest ILK deficient cells subsequently exited from mitosis or died." (PMID 24911651, 2014). "PARVB, encodes beta-parvin, which negatively regulates integrin-linked kinase (ILK) activity in breast cancer cells." (PMID 19924294, 2009). "For example, integrin-linked kinase (ILK), which is either activated or overexpressed in many types of cancers including breast cancer, can remarkably reduce the protein stability of Notch1 and thus decrease its half-life drastically." (PMID 19468305, 2009). "Another study identified integrin-linked kinase (ILK) as a signaling molecule that may control stiffness-mediated doxorubicin resistance in breast cancer cells." (PMID 39409910, 2024). "Similarly, for biological pathways, we found that the predicted UR and DR genes were enriched in pathways associated with breast cancer, such as the ILK pathway and the Rho GTPase signaling pathway." (PMID 34991439, 2022). "Additionally, tissue stiffness regulates integrin-linked kinase (ILK) expression to control stem-like breast cancer cells under hypoxic conditions." (PMID 33050609, 2020). "Interestingly, AE suppressed YB-1 expression through the downregulation of the intracellular integrin-linked kinase (ILK)/protein kinase B (Akt)/mTOR signaling pathway in HER-2-overexpressing breast cancer cells." (PMID 27391337, 2016).
breast cancer (continued). "However, other authors have reported that integrin signaling can induce Snail and Slug expression in other cancer models, for example, ILK increases Snail expression in non-small cell lung cancer, while integrin αvβ3 induces Slug in breast cancer with effects linked to stemness." (PMID 35682554, 2022). "Increased levels of focal adhesion proteins palladin, zyxin, integrin-linked protein kinase (ILK) and the adherens junction protein nexilin, are consistent with GC-stimulated formation of adherens junctions and tight junctions, previously observed in TM cells and in mammary tumor cells." (PMID 22876128, 2012). "Patients' tissue samples revealed that ILK mRNA expression was significantly elevated in breast cancer tissues compared to the adjacent normal tissues." (PMID 41537745, 2026). "In breast cancer cells, NETs have been shown to bind to the CCDC25 receptor, thereby increasing cell motility in mice via the integrin-linked kinase (ILK) pathway." (PMID 38419052, 2024). "Under hypoxic conditions, OPN triggers integrin-linked kinase (ILK)/Akt-mediated NF-κB activation, which results in HIF-1α-dependent VEGF expression in breast cancer cells and subsequent angiogenesis." (PMID 39062100, 2024). "Parvb is considered as a tumor suppressor gene, and inhibits breast cancer growth; decreased expression of PARVB in breast cancer cells results in elevated ILK protein and kinase activity levels, suggesting that Parvb downregulation stimulates ILK signaling." (PMID 38374196, 2024). "It has been found that upregulation of ILK leads to significant acceleration of tumor development in breast cancer." (PMID 34991439, 2022). "The experiments were performed to investigate the drug resistance mechanism of GDC-0941 and the effect of the combination of GDC-0941 and ILK inhibitors on breast cancer." (PMID 35477364, 2022). "Tumor formation and metastasis increase with tissue stiffness in ovo and ILK depletion in this context abolishes the invasiveness and metastatic potential of breast cancer cells." (PMID 35804980, 2022). "Targeting the ILK signaling axis results in inhibition of phosphorylation of Akt and GSK3β in breast cancer, ovarian cancer, and hepatocarcinoma, among others." (PMID 35804980, 2022). "A variety of breast cancer cells were selected and transfected with ILK or shILK, as well as treated with GDC-0941, OSU-T315, or TNF-α antibody for the in vitro studies." (PMID 35477364, 2022). "The IC50 for GDC-0941 was elevated when ILK was overexpressed and was decreased after ILK knockdown, indicating that ILK expression was indeed related to the sensitivity of breast cancer cells to GDC-0941." (PMID 35477364, 2022). "Breast cancer cells cultured on polyacrylamide hydrogels of varying stiffness were observed to show differential levels of ILK expression." (PMID 35804980, 2022). "That is, upregulation of ILK expression level leads to drug resistance of GDC-0941, while downregulation of ILK expression level increases the sensitivity of breast cancer cell lines to GDC-0941." (PMID 35477364, 2022). "ILK was transfected into MCF7 and MDA-MB-453 cells, while shILK was transfected into MDA-MB-231 and HCC1937 cells to investigate the role of ILK in the sensitivity of breast cancer cell lines to GDC-0941." (PMID 35477364, 2022). "ILK phosphorylates GSK3β at Ser9 in breast cancer, affecting the activation of the transcription factor AP1 and the stabilization of β-catenin, which is indirectly related to deregulation of proliferation, migration, and differentiation." (PMID 35379935, 2022). "Ectopic expression of ILK in epithelial breast cancer cells decreases the number and volume of autophagosomes when cells are grown on soft substrata, relative to stiff matrices, suggesting a role of ILK in regulating autophagy during dormancy." (PMID 35804980, 2022). "Over-expression of integrin-linked-kinase (ILK) promotes proliferation and growth of breast cancer cells." (PMID 34991439, 2022).
breast cancer (continued). "It has been reported that ILK gene knockout can inhibit the invasion and metastasis of Renal Cell Carcinoma and breast cancer, and is also an attractive target for the treatment of ovarian cancer." (PMID 35587162, 2022). "Knockdown of ILK expression in breast cancer cells suppresses pericytic spreading of disseminated cancer cells (DCC) and inhibits metastatic colonization of the brain, lungs, and bone." (PMID 35804980, 2022). "In this study, we selected the ILK inhibitors OSU-T315 or TNF-α antibody in combination with GDC-0941 to study their therapeutic effects on breast cancer." (PMID 35477364, 2022). "Cancer cell-derived factors, Wnt7a via TGF-β-dependent signaling in breast cancer and galectin-3 via integrin beta 1/ILK/NF-κB signaling in pancreatic cancer, have been reported to be involved in the malignant transformation of fibroblasts and stellate cells." (PMID 34885065, 2021). "These authors showed that EV-associated ILK is sufficient to promote EMT and metabolic reprogramming in recipient mammary epithelial cells, thus highlighting the key role of EV cargo in breast cancer progression." (PMID 34205051, 2021). "A recent study identified a central driver of EMT, integrin-linked kinase (ILK), as a cargo of CD63 positive (CD63+) EVs secreted from breast cancer cells." (PMID 34205051, 2021). "Bioinformatics analyses revealed that all six top canonical pathways, including the signallings of Actin cytoskeleton, ILK, VEGF, BAG2, Integrin, and Paxillin, are associated with the migration of breast cancer cells." (PMID 34571787, 2021). "ILK mediates integrin signalling by connecting the cytoplasmic domains of β-integrins to the actin cytoskeleton to regulate the migration of breast cancer, and thus promotes cell survival." (PMID 34571787, 2021). "Hypoxic breast cancer cells promote tumor spreading by releasing exosomes, which induce mitochondrial reprogramming, ILK-Akt activation and malignant morphogenesis in normal mammary epithelial cells." (PMID 33672100, 2021). "Inhibition of ILK activity by Cpd22 has been shown to suppress the viability of prostate and breast cancer cells." (PMID 32260415, 2020). "Another substrate of PAK1, Integrin-linked kinase (ILK), can be phosphorylated by PAK1 at threonine 173 and serine 246 to promote breast cancer cell motility and proliferation." (PMID 32863957, 2020). "Breast cancers acquire aggressive capabilities via epithelial to mesenchymal transition (EMT), in which various integrins/integrin-linked kinase signalling are upregulated." (PMID 33276802, 2020). "Inactivating ILK, FAK, MAPK, or PI3K/AKT signalling would also suppress EMT, so the ITGB1-FAK/ILK axis revealed by proteomic inquires conducts the TWIST-induced EMT in human breast cancer cells." (PMID 31781477, 2019). "For example, syndecan-1 that is expressed on AML cells, is a therapeutic target under investigation in multiple myeloma, while the inhibition of ILK has been tested in chronic lymphocytic leukaemia, prostate, and breast cancer cell lines." (PMID 30658474, 2019). "In that regard, previous studies showed that KLF5 promotes breast cancer cell migration and invasion by upregulating transcription of TNFAIP2, and that KLF5 controls keratinocyte migration via the integrin-linked kinase." (PMID 31327760, 2019). "In MCF7 breast cancer cells, knockdown of FAK, Integrin linked kinase (ILK), Talin, and Zyxin leads to enlarged FAs." (PMID 28476046, 2017). "Consistent with ILK exerting control over cell differentiation programming, ILK perturbation in the breast cancer cell line MDA-MB-231 resulted in impaired cell migration and reduced expression of mesenchymal markers such as α-smooth muscle actin." (PMID 28106780, 2017). "In the same study, breast cancer patients with more intense immunostaining for ILK had lower 5-yr survival than patients with low ILK levels." (PMID 28391240, 2017).